MC1R (melanocortin 1 receptor)
Diseases named in the same sentence as MC1R in open-access papers (continued):
Sharing a sentence is not in itself a finding about the gene and the disease.
glomerular disease (2 papers, 2014 to 2016). "Therefore, more conclusive evidence, such as the use of mutants with selective MCR deficiency, is essential to define and validate the role of MC1R in mediating the beneficial effect of melanocortin therapy in glomerular disease." (PMID 27270328, 2016). "Together, the human expression data and experimental data in rats propose a role for MC1R agonists in treating glomerular disease." (PMID 24498203, 2014). "Whether the MC1R-independent beneficial effect of melanocortin therapy could be generalized to other forms of long-term experimental glomerulopathy, such as Adriamycin nephropathy, is unknown and warrants further investigation." (PMID 27270328, 2016).
Hepatic steatosis (2 papers, 2023 to 2024). Steatosis is a term used to denote lipid accumulation within hepatocytes. "Collectively, these expression analyses suggest that hepatic MC1R deficiency enhances de novo lipogenesis and fatty acid esterification, leading to excessive accumulation of TGs and hepatic steatosis." (PMID 39117851, 2024). "Hepatocyte-specific MC1-R deficiency increased plasma cholesterol and TG concentration, disturbed BA metabolism, and led to signs of hepatic steatosis and fibrosis." (PMID 37490042, 2023). "Because there is a reciprocal interaction between fatty liver disease and dysregulated BA metabolism, it is difficult to determine whether MC1-R deficiency per se disturbs BA metabolism or whether enhanced lipid accumulation in Mc1r LKO mice causes a defect in BA metabolism." (PMID 37490042, 2023).
keloid (2 papers, 2021 to 2025). An irregularly shaped, elevated mark on the skin caused by deposits of excessive amounts of collagen during wound healing. "They found reduced expression of MC1R in dermal fibroblasts in keloid scars." (PMID 41002740, 2025).
kidney damage (2 papers, 2014 to 2015). "The beneficial effects of α-MSH and MS05 in this model, and the lack of significant effect of ACTH, suggests MC1R agonism, in the absence of MC2R agonism, might protect against kidney damage, on the basis that MC1R agonists decrease measures of oxidative stress." (PMID 25323206, 2015).
membranous nephropathy (2 papers, 2014 to 2020). "In a rodent model of membranous nephropathy (passive Heymann nephritis), an MC1R agonist improved proteinuria and glomerular morphology." (PMID 32539845, 2020). "We have confirmed our previous findings that MC1R agonists can ameliorate passive Heymann nephritis mimicking human membranous nephropathy (MN)." (PMID 24498203, 2014). "In our previous paper we showed that MC1R agonist treatment could ameliorate experimental membranous nephropathy in rats." (PMID 24498203, 2014).
osteoarthritis (2 papers, 2014 to 2025). A noninflammatory degenerative joint disease occurring chiefly in older persons, characterized by degeneration of the articular cartilage, hypertrophy of bone at the margins and changes in the synovial membrane. "Activation of MC1R and MC3R via agonists can be used to counter inflammatory and degenerative changes in rheumatoid and osteoarthritis." (PMID 41002740, 2025).
thyroid cancer (2 papers, 2023 to 2025). "Pan-cancer analysis showed that CCDC68, FAM151A and MC1R were significantly different in thyroid cancer (THCA), renal clear cell carcinoma (RCC) and lung squamous cell carcinoma (LUSC) etc.." (PMID 40547309, 2025).
actinic keratosis (1 paper, 2023). A precancerous lesion of the skin composed of atypical keratinocytes. "Multivariable models revealed a 7.5-fold risk of developing NMSC in individuals with actinic keratosis; 4.1- or 3.6-fold in those with green or blue eyes, respectively; and a 1.9-fold increased risk in the MC1R medium- + high-risk group." (PMID 36765822, 2023).
age-related macular degeneration (1 paper, 2025). Age-related loss of vision in the central portion of the retina (macula), secondary to retinal degeneration. "In the human retinal pigment epithelium cell line, binding of α MSH to MC1R can cause the activation of Akt–mTOR signaling and diminished oxidative stress and risk of age-related macular degeneration (AMD)." (PMID 41002740, 2025).
allergic rhinitis (1 paper, 2024). Inflammation of the nasal mucous membranes caused by an IgE-mediated response to external allergens. "With the growing body of evidence demonstrating the role of MC1R regulation in the treatment of allergic rhinitis and asthma, the effect of α-MSH supplementation in immunological regulation in allergic conjunctivitis has been recently explored." (PMID 38397406, 2024).
Anxiety (1 paper, 2024). Intense feelings of nervousness, tension, or panic often arise in response to interpersonal stresses. "The study found that participants with the MC1R gene variant reported significantly higher levels of dental care-related anxiety and fear of dental pain, and were more likely to avoid dental care than those without the variant, even after controlling for general anxiety levels and sex." (PMID 38975446, 2024). "Similarly, another set of researchers conducted a study to investigate whether having a natural red hair color, a variant of the MC1R gene, or both, could predict a patient's experience of dental care-related anxiety and avoidance." (PMID 38975446, 2024).
autoimmune uveitis (1 paper, 2025). An autoimmune form of uveitis (disease). "Recent studies have suggested that MC1R and MC5R can be therapeutic targets to suppress autoimmune uveitis." (PMID 41002740, 2025).
Brain atrophy (1 paper, 2021). Partial or complete wasting (loss) of brain tissue that was once present. "Moreover, MC1R activation with BMS-470539 reduced brain atrophy and improved long-term neurological function at 28 days post-HI." (PMID 33468172, 2021). "Secondly, activation of MC1R with BMS-470539 significantly reduced infarct area and brain atrophy, and improved short- and long-term neurological deficits post-HI." (PMID 33468172, 2021). "Activation of MC1R with BMS-470539 significantly reduced the percent infarct area, brain atrophy, and inflammation, and improved short- and long-term neurological deficits at 48 h and 28 days post-HI." (PMID 33468172, 2021).
brain inflammation (1 paper, 2022). "Despite the previously reported expression of MC1R in a human astrocyte cell line and suggested glial cell MC1R-mediated inhibition of TNF-α by α-MSH in a mouse model of brain inflammation, our double-labeling showed rare colocalization of MC1R and GFAP." (PMID 35197079, 2022).
choroidal melanoma (1 paper, 2022). Malignant tumor of melanocytes of the choroid. "Interestingly, melanogenic activity was observed in cultured human choroidal melanoma cells but not in choroidal melanocytes from healthy individuals, and human uveal melanocyte cell lines derived from human choroids and iris revealed that uveal melanocytes do not express MC1R." (PMID 35547230, 2022).
cognitive decline (1 paper, 2021). "Instead, the MC1R and the MC3R, which have higher expression levels in the hippocampus than the MC4R and showed statistically significant correlations with the performance of aged rats in spatial learning and memory, may be better drug targets for the aging-related cognitive decline." (PMID 34684847, 2021).
congestive heart failure (1 paper, 2025). Failure of the heart to pump a sufficient amount of blood to meet the needs of the body tissues, resulting in tissue congestion and edema. "Echocardiographic measurements showed reduced EF and radial strain rate in Mc1r‐cKO mice after 8 weeks of TAC surgery, but no change in stroke volume or lung weight, suggesting that cardiomyocyte‐specific MC1R deficiency does not predispose to congestive heart failure." (PMID 39921516, 2025).
deafness (1 paper, 2010). An inherited or acquired condition characterized by the complete loss of the ability to hear from one or both ears. "However, if the red coat colour in ASCD is in fact linked to deafness and speckled coat colour in the ASCD, none of the currently reported loci causing red coat colour, such as the Mc1r locus on CFA5, are the cause of red coat colouration in the ASCD." (PMID 20967282, 2010).
dermatitis (1 paper, 2025). An inflammatory process affecting the skin. "MC1R polymorphisms have been associated with altered immune response profiles and may contribute to variations in susceptibility to autoimmune diseases and skin disorders." (PMID 41002740, 2025).
dilatation (1 paper, 2025). "Instead, cardiomyocyte‐specific MC1R deficiency led to enhanced LV dilatation and to abnormalities in LV systolic and diastolic function after TAC surgery." (PMID 39921516, 2025).
experimental autoimmune encephalomyelitis (1 paper, 2019). An autoimmune demyelinating disease of the central nervous system that is produced experimentally in animals by the injection of homogenized brain or spinal cord in Freund's adjuvant. "Recently, melanocortin-1 receptor (Mc1r) activation by Nle4-D-Phe7-α-MSH (NDP-MSH) was shown to play a neuroprotective role in an experimental autoimmune encephalomyelitis (EAE) mouse model." (PMID 31660977, 2019). "Likewise, the administration of NDP-MSH ameliorated blood-brain barrier (BBB) disruption by activating Mc1r in a model of experimental autoimmune encephalomyelitis (EAE)." (PMID 31660977, 2019).
Granuloma (1 paper, 2020). A compact, organized collection of mature mononuclear phagocytes, which may be but is not necessarily accompanied by accessory features such as necrosis. "Since α-MSH belongs to MC1R agonist family, we used an anti-MC1R antibody to assess the western blots in PBMCs, granulomas, and granulomas treated with α-MSH cells." (PMID 32350353, 2020).
heart failure (1 paper, 2025). Inability of the heart to pump blood at an adequate rate to meet tissue metabolic requirements. "The level of MC1R protein was significantly reduced in TAC‐operated mice after 4 weeks, and it progressively declined toward a more advanced stage of pathological hypertrophy and heart failure (8 weeks after TAC)." (PMID 39921516, 2025).
hematoma (1 paper, 2019). A hematoma is a collection of blood from a vascular structure into an extravascular space. "Double immunofluorescence staining showed that Mc1r was mainly expressed in the microglia, astrocytes, and endothelial cells in the peri-hematoma tissue at 24 h after ICH." (PMID 31660977, 2019). "The Mc1r expression in the peri-hematoma tissue was significantly increased at 24 h and reached its peak at 72 h after ICH, when compared to the sham group." (PMID 31660977, 2019).
hemochromatosis (1 paper, 2011). A disorder of iron metabolism characterized by a triad of HEMOSIDEROSIS; LIVER CIRRHOSIS; and DIABETES MELLITUS. "We expect CDH is generalizable to some of the known examples, such as HFE and hemochromatosis, where both the allele effect sizes and frequencies are comparable to MC1R alleles." (PMID 22140526, 2011).
hypoxic-ischemic encephalopathy (1 paper, 2023). "The findings suggest that MC1R activation could be a promising therapeutic target for the treatment of hypoxic-ischemic encephalopathy (HIE) in newborns." (PMID 37569558, 2023).
injury (1 paper, 2021). Damage inflicted on the body as the direct or indirect result of an external force, with or without disruption of structural continuity. "Therefore, to demonstrate that MC1R, and not other MCRs, play anti-inflammatory and neuroprotective effects in HI brain injury, a specific selective agonist of MC1R, BMS-470539, was used in our study." (PMID 33468172, 2021).
Left ventricular dilatation (1 paper, 2025). Enlargement of the chamber of the left heart ventricle. "However, MC1R knockout mice subjected to pressure overload showed left ventricular dilatation that was associated with reduced ejection fraction and changes in left ventricular diastolic function." (PMID 39921516, 2025).
Leukocytosis (1 paper, 2021). "Despite robust leukocytosis, atherosclerotic plaque size and composition as well as arterial leukocyte counts were unaffected by MC1-R deficiency." (PMID 34868038, 2021).
Lewis lung carcinoma (1 paper, 2023). "Pro-opiomelanocortin gene delivery blocked the growth of alpha-melanocyte-stimulating hormone/melanocortin 1 receptor (MC1R)-deficient Lewis lung carcinoma cells as well as the growth of these cells in mice; apoptotic mechanisms mediated these effects through an MC1R-independent pathway." (PMID 37509632, 2023).
liver fibrosis (1 paper, 2024). "MC1R deficiency also promoted signs of liver fibrosis, inflammation and apoptosis, which are pathological hallmarks of progression from simple steatosis to steatohepatitis." (PMID 39117851, 2024). "Overall, the in vitro data suggest that hepatocyte-specific loss of MC1R could directly promote liver fibrosis and apoptosis, but the pathological hallmarks of NAFLD, i.e. apoptosis, inflammation and fibrosis, might also be a consequence of increased TG accumulation in the liver." (PMID 39117851, 2024).
multiple sclerosis (1 paper, 2022). A progressive autoimmune disorder affecting the central nervous system resulting in demyelination. "The same study reported reduced brain MC1R expression in multiple sclerosis patients, although no brain regions or neuron types were specified." (PMID 35197079, 2022).
nonalcoholic fatty liver disease (1 paper, 2023). "(E) MC1R gene expression in human liver biopsies from control cases (n=10) and patients with nonalcoholic fatty liver disease (NAFLD, n=51) or nonalcoholic steatohepatitis (NASH, n=155)." (PMID 37490042, 2023).
nonalcoholic steatohepatitis (1 paper, 2023). "Furthermore, using RNA sequencing data from human liver biopsies, we found that hepatic MC1R expression was significantly downregulated (log2 fold change = −1.1) in patients with NAFLD or nonalcoholic steatohepatitis (NASH) compared to control cases." (PMID 37490042, 2023).
Parkinson (1 paper, 2025). "Using data from the Parkinson's Progression Markers Initiative (PPMI) cohort, we aimed to test whether MC1R loss-of-function variants, especially those previously associated with an increased risk of PD, are associated with PD progression and phenoconversion." (PMID 41503455, 2025).
rosacea (1 paper, 2018). A chronic erythematous skin disorder that affects the face. "This study in individuals of 97% European ancestry has identified significant associations with rosacea genes previously implicated in skin pigmentation (HERC2-OCA2, SLC45A2, IRF4 and MC1R)." (PMID 29771307, 2018).
skin aging (1 paper, 2023). The gradual irreversible changes in structure of skin that occur as a result of the passage of time.. "Risk factors for developing NMSC include lighter phenotype, holiday-related high UVR, specific MC1R variants, and the presence of AK, but not skin aging per se." (PMID 36765822, 2023).
skin toxicity (1 paper, 2021). "The high frequency of the melanocortin 1 receptor Single Nucleotide Polymorphism, specifically mutations in the R160 W allele, was associated with the presence of severe acute skin toxicity, suggesting a relationship between dark skin color and the presence of this adverse event." (PMID 34678859, 2021).
synucleinopathies (1 paper, 2022). "Collectively, these results show exacerbated synucleinopathies in the nigrostriatal pathway resulting from MC1R loss of function in a αSyn AAV mouse model." (PMID 35197079, 2022).
systemic inflammatory response syndrome (1 paper, 2023). SIRS is a serious condition related to systemic inflammation, organ dysfunction, and organ failure. "Mutations in MC1R lead to an augmented inflammatory response and are associated with burn-induced systemic inflammatory response syndrome (SIRS) and infectious complications in patients." (PMID 37957462, 2023).
Xeroderma pigmentosum complementation group C (1 paper, 2022). "Genes also involved in NMSCs pathogenesis are melanocortin-1 receptor (MC1R), xeroderma pigmentosum complementation group C (XPC), cytochrome P450 2D6 (CYP2D6), cyclin dependent kinase inhibitor 2A (CDKN2A), glutathione S-transferase theta 1 gene (GSTT1), and telomerase." (PMID 36291078, 2022).
tumor (65 papers, 2002 to 2026). "The coinjection of DOTA-NAPamide led to significant loss of uptake in the MC1R-expressing B16/F1 tumor xenografts." (PMID 31163066, 2019). "Adjusted odds ratios (ORs) and 95% confidence intervals (CIs) for the associations between MC1R variants and histopathological tumor characteristics among first incident cases of invasive melanoma in the GEM Study." (PMID 25790105, 2015). "In univariate analyses, we compared the distributions of MC1R genotype risk categories across strata of prognostic tumor characteristics including: Breslow thickness and presence of mitoses, ulceration, or TILs." (PMID 25790105, 2015). "We also evaluated other histopathological tumor features for associations with MC1R variation in an effort to further characterize potential etiologic heterogeneity." (PMID 25790105, 2015). "Adjusted odds ratios (ORs) and 95% confidence intervals (CIs) for the associations between MC1R variants and prognostic histopathological tumor characteristics among first incident cases of invasive melanoma in the GEM Study, stratified by phenotype." (PMID 25790105, 2015). "There was a small but significant inverse association between MC1R score and log Breslow thickness (estimate −0.02, P-value = 0.03) in cases whose tumor was thicker than 0.75 mm over all 10 cohorts, adjusted for center." (PMID 22325793, 2012). "Those with a higher tumor burden more often carried medium- or high-risk MC1R variants." (PMID 36765822, 2023). "In addition to MC1R, we identified several genes that had a high mutational burden compared with the tumor-free controls." (PMID 37444464, 2023). "In the absence of skin aging contributing to NMSC development, certain MC1R risk types may identify OTR at risk for high tumor burden." (PMID 36765822, 2023). "We next considered whether the increased number of mutations observed in tumours from MC1R variant carriers could be due to differential DNA repair ability in primary human melanocytes (HPMs)." (PMID 27403562, 2016). "Thus, MC1R polymorphisms can exacerbate the UV-induced DNA damage and promote tumor formation." (PMID 32429485, 2020). "In the biodistribution study, [125I]NpG-GGN3b showed the second-highest tumor accumulation among the four radioiodinated α-MSH analogs despite having the lowest affinity for MC1R." (PMID 39828865, 2025). "Consistent with the MC1R affinity determined in an in vitro study, [125I]NpG-GGN4b exhibited significantly higher accumulation in the tumor than [125I]NpG-GGN3b (p < 0.05) and was comparable to [111In]In-DOTA-GGNle-CycMSHhex." (PMID 39828865, 2025). "Together, by stimulating the expression of MC1R accompanied with its ligand α-MSH treatment, MC1R signaling is further amplified to dampen tumor growth, proposing targetable vulnerability for HCC therapy." (PMID 40473594, 2025). "The results indicated that the high affinity of [211At]NpG-GGN4c contributed to high MC1R-specific accumulation in the tumor." (PMID 39828865, 2025). "A theranostic approach is employed, based on targeted delivery of a radioactively labeled peptide (active pharmaceutical ingredient, antibody-based API) to the tumor, where the highly overexpressed MC1R is activated on the cell surface." (PMID 40843729, 2025). "Next, we tried to uncover the functional role of MC1R in cancer cell proliferation and tumor growth." (PMID 40473594, 2025). "MC1R functions as a tumor suppressor by triggering phosphorylation of YAP and inhibiting its activity in both ligand dependent and independent manners." (PMID 40473594, 2025). "The high accumulation of [211At]NpG-GGN4c in the tumor was significantly reduced by MC1R inhibition (p < 0.05)." (PMID 39828865, 2025). "One of the most promising tumor cell surface markers is melanocortin 1 receptor (MC1R), a G-protein coupled receptor that has a pivotal role in melanogenesis and skin pigmentation due to the binding of its ligand, α-Melanocyte Stimulating Hormone (α-MSH)." (PMID 38256168, 2024).